DPY19L2 (dpy-19 like 2)
Diseases named in the same sentence as DPY19L2 in open-access papers:
DPY19L2 is named in the same sentence as 10 diseases in open-access papers, as found by Europe PMC text mining. Sharing a sentence is not in itself a finding about the gene and the disease. The quoted sentences say what the papers report.
Globozoospermia (41 papers, 2012 to 2025). Any structural anomaly of the acrosome resulting in a round sperm head. "In two patients, with globozoospermia, pathogenic variants in the DPY19L2 gene were found: one with a homozygous deletion of the complete gene and one with a combination of a heterozygous deletion of the DPY19L2 gene and a hemizygous frameshift variant." (PMID 39180390, 2025). "In humans, the deletion of DPY19L2 causes globozoospermia, a male infertility condition characterized by round-headed spermatozoa due to defective sperm head elongation and acrosome formation." (PMID 40583721, 2025). "DPY19L2 is the most common gene involved in the etiology of globozoospermia, and the more common pathogenic variant is the deletion of the entire gene, which has been reported to have a prevalence ranging from 22.2% to 83.3%." (PMID 39045326, 2024). "Currently, both recessive deletions and mutations in DPY19L2 seem to be the main cause of globozoospermia." (PMID 38790229, 2024). "In other individual with partial globozoospermia (patient 10), the detected DPY19L2 gene variant is also VoUS, which requires additional evaluation of pathogenicity." (PMID 39045326, 2024). "Mutations or deletions in SPATA16, PICK1 and DPY19L2 can cause sperm DNA damage and subsequently cause globozoospermia when sperm repair is abnormal." (PMID 37529603, 2023). "Examination of mouse FAM209-associated proteins detected DPY19L2, a protein that contains ten transmembrane domains, is localized to the inner nuclear envelope and was first found to be implicated in globozoospermia of infertile men ∼10 years ago." (PMID 34471926, 2021). "Among the globozoospermia-associated genes analyzed in the literature, DPY19L2 is the most frequently mutated gene in affected patients from different ethnic and geographic origins." (PMID 34209343, 2021). "The remaining three samples were from globozoospermia patients, C3, C4, and C5, who carried either deletions and/or point mutations in DPY19L2." (PMID 33809228, 2021). "DPY19L2 was the first inner nuclear envelope protein shown to be essential for anchoring the acrosome to the nucleus and has been implicated in globozoospermia in the majority of patients analyzed." (PMID 34471926, 2021). "Probable C-mannosyltransferase DPY19L2 has been implicated in globozoospermia in infertile men (spermatogenic failure type 9) and localizes to the inner nuclear envelope in the region of the developing acrosome." (PMID 34471926, 2021). "Globozoospermia is commonly caused by recessive deletions of DPY19L2, but a significant fraction of all patients remain undiagnosed." (PMID 31985809, 2020). "In humans, mutations in only two genes have been clearly demonstrated to cause globozoospermia: DPY19L2, in which most of known causative mutations have been found, and SPATA1618–20." (PMID 29991750, 2018). "A Dpy19L family member, Dpy19L2, which is a causative gene for human Globozoospermia, is suggested to act as an anchor of the acrosome to the nuclear envelope." (PMID 27959946, 2016). "Recently, a DPY19L2 deletion has been found to cause human globozoospermia, which is a severe male infertility disorder resulting from round-headed spermatozoa." (PMID 27959946, 2016). "Among these members, Dpy19L2 is the most well-studied gene, since DPY19L2 is a causative gene responsible for human globozoospermia, which is a severe and rare male infertility disorder." (PMID 27959946, 2016). "DPY19L2 gene deletion was considered as the molecular pathogenic factor for the onsetof globozoospermia in infertile men." (PMID 27441053, 2016). "We demonstrated recently that DPY19L2 was in fact the main locus associated with globozoospermia as 15 out of 20 analysed patients presented a 200 Kb homozygous deletion removing the entire gene." (PMID 25780569, 2013).
Globozoospermia (continued). "We demonstrated recently that DPY19L2 was in fact the main locus associated with globozoospermia as 15 out of 20 analysed patients presented a 200 Kb homozygous deletion removing the totality of the gene." (PMID 23555282, 2013). "Here we focus on the DPY19L2 locus (12q14.2) which has recently been shown to be linked with Globozoospermia, a rare syndrome of male infertility characterized by the presence of 100% round, acrosomeless spermatozoa in the patient's ejaculate (MIM #102530)." (PMID 23555282, 2013). "In conclusion, according to the evidence reported so far, besides DPY19L2, other genes that might be confidently associated with globozoospermia in humans, and whose analysis might be recommended in clinical practice, are SPATA16, PICK1, ZPBP1, and CCDC62." (PMID 38790229, 2024). "DPY19L2 as the most frequent causative gene was reported to be associated with globozoospermia." (PMID 38310235, 2024). "Variants of the DPY19L2 gene can cause both complete and partial globozoospermia." (PMID 39045326, 2024). "Deletion of Dpy19l2 in mice leads to globozoospermia and acrosome loss." (PMID 34471926, 2021). "Globozoospermia is most commonly caused by mutations in the DPY19L2 gene (BR35)." (PMID 32318024, 2020). "After pre-screening 16 men for mutations in known globozoospermia genes DPY19L2 and SPATA16, exome sequencing was performed in 15 males with globozoospermia or acrosomal hypoplasia of unknown aetiology." (PMID 31985809, 2020). "In gene KO mouse studies, various genes (Atg7, Csnk2a2, Dpy19l2, Gba2, Golga2, Gopc, Hrb, Hsp90b1, Mfsd14a, Pick1, Sirt1, Slc9a8, Smap2, Spaca1, Tmf1, Vps54, Zpbp1) were found to be associated with globozoospermia." (PMID 29065458, 2017). "Therefore, we investigated complete deletion of DPY19L2 gene effects to reaffirm the potential association of DPY19L2 gene and globozoospermia." (PMID 27441053, 2016). "In addition, the defect of DPY19L2 gene was the main genetic cause of human globozoospermia, which may be related to the defect of chromatin compaction during spermatogenesis and sperm DNA damage." (PMID 35464385, 2022). "Therefore, DPY19L2 was found to be a major causative gene of globozoospermia in humans." (PMID 29065458, 2017). "Human genes thathave been largely associated with globozoospermia include proteins interactingwith C kinase 1 (PICK1), SPATA16, zonapellucida binding protein 1 (ZPBP1), and Dpy-19-like-2(DPY19L2)." (PMID 40833973, 2025). "In partial globozoospermia, mutations were found in the DPY19L2 and SPATA16 genes affected in patients with ‘classic’ globozoospermia." (PMID 39045326, 2024). "Homozygous DPY19L2 and SPATA16 variants were identified in two patients with partial globozoospermia and one patient with complete globozoospermia." (PMID 39045326, 2024). "Globozoospermia is further related to the deletion of the DPY19L2 gene, contributing to the inaccurate stabilization of the acrosome." (PMID 35163651, 2022). "In humans, several genes have been associated with teratozoospermia, including SPATA16, DPY19L2, PICK1, ZPBP1, and CCDC62, that are linked to globozoospermia." (PMID 33880962, 2022). "In humans, deletion of the DPY19L2 gene leads to globozoospermia, a condition in which spermatozoa show a monomorphic rounded head." (PMID 33880962, 2022). "The most common abnormality is variation in the DPY19L2 gene, while variations in the SPATA16, PICK1 and GGN have also been investigated as causes of globozoospermia." (PMID 34361119, 2021). "Analyzing the reported percentage of DPY19L2 mutations, together with those of the two other globozoospermia-associated genes SPATA16 and PICK1, more than half of the cases carried DPY19L2 mutations, with a rather lower frequency of SPATA16 or PICK1 mutations." (PMID 34209343, 2021).
Globozoospermia (continued). "In particular, recessive deletions and point mutations of three genes, dpy-19-like 2 (DPY19L2), spermatogenesis associated 16 (SPATA16) and protein interacting with C Kinase (PICK 1) result in globozoospermia phenotype." (PMID 33155089, 2021). "Our genetic analysis of 3 CG men confirmed a deletion of 3 genes—DPY19L2, SPATA16, and PICK1—which are often associated with the globozoospermia phenotype and contribute to the most relevant feature of this condition, the absence of acrosome." (PMID 33877510, 2021). "Analysis of the FAM209 proteome identified DPY19L2, whose human orthologue is involved in the majority of globozoospermia cases." (PMID 34471926, 2021). "Although pathogenic variants in DPY19L2 and SPATA16 are known causes of globozoospermia and explain up to 70% of all cases, genetic causality remains unexplained in the remaining patients." (PMID 31985809, 2020). "A subset of genetic mutations, such as DNAH6, SPATA16, DPY19L2, PICK1, and CCIN related to globozoospermia, have been reported in the past few years." (PMID 32582379, 2020). "Of interest, ZPBP forms part of the same gene interaction network with known globozoospermia genes SPATA16 and DPY19L2, thus suggesting they are mechanistically linked." (PMID 31985809, 2020). "Only, four genes have been so far detected in individuals presenting globozoospermia including DPY19L2, SPATA16, PICK1 and Calicin." (PMID 30291685, 2019). "In human, both copies of the DPY19L2 gene are deleted in around 70% of men with globozoospermia, a rare phenotype characterised by malformed round sperm heads without an acrosome." (PMID 29946470, 2018). "Next, the onset of Spata16 expression was examined by RT-PCR and compared with that of globozoospermia-related genes: Dpy19l2, Pick1, and Spaca1." (PMID 29065458, 2017). "In thisstudy, further to 14 (out of 18) individuals who hadshown some deletion in DPY19L2 gene, six (out ofnine) new cases with globozoospermia, missed theentire length of DPY19L2 gene (G21, 22, 23, 24, 26 and 27)." (PMID 27441053, 2016). "Researchers have recently identified a large deletion, about 200 kbp,encompassing the whole length of DPY19L2 or mutations in SPATA16 and PICK1 genesassociated with globozoospermia." (PMID 27441053, 2016). "In our previous work we had demonstrated that DPY19L2 was homozygously deleted in a majority of patients with globozoospermia and that this deletion occurred by NAHR between two highly homologous 28 Kb LCRs located on each side of the gene." (PMID 23555282, 2013). "We then identified DPY19L2 point mutations and heterozygous deletions and demonstrated that 84% of the 31 globozoospermia patients analysed had a molecular alteration of DPY19L2." (PMID 23555282, 2013). "When CNV data from Patient Three was observed using CNViewer across the known globozoospermia disease loci, only the DPY19L2 locus was found to be affected by a homozygous deletion." (PMID 22912880, 2012). "Pathogenic variants in the DPY19L2 gene in compound heterozygous or homozygous state have been described in patients with spermatogenesis disorder type 9, SPGF9 (OMIM: 613958) associated with globozoospermia." (PMID 39045326, 2024). "Three infertile patients (one man with complete globozoospermia and two ones with partial globozoospermia) underwent whole exome sequencing (WES), which revealed nucleotide sequence variants in the DPY19L2 and SPATA16 genes that relevant to globozoospermic phenotype." (PMID 39045326, 2024). "Additionally, DPY-19-like 2 (DPY19L2), a key causative factor related to human globozoospermia was also found in the PT network." (PMID 35252197, 2022). "Therefore, the aim of our study was to investigate the genetic contribution of the main globozoospermia-associated genes (SPATA16, PICK1 and DPY19L2) in 18 unrelated Italian men." (PMID 34209343, 2021). "All six patients carrying deletions in the DPY19L2 gene showed complete globozoospermia." (PMID 34209343, 2021).
Globozoospermia (continued). "Although mutations in human and mouse Dpy19l2 have been shown to cause globozoospermia, no in vivo interacting partners of DPY19L2 have been identified until now." (PMID 34471926, 2021). "The causes of globozoospermia are genetic and, as far as we are currently aware, involve mutations in three genes, SPATA16 (spermatogenesis associated 16), PICK1 (protein interacting with PRKCA 1) and DPY19L2 (DPY-19 like 2) with the latter being dominant." (PMID 33101214, 2020). "The majority of mutations leading to human globozoospermia identified so far are linked to DPY19L2, but several patients remain without a genetic diagnosis." (PMID 29991750, 2018). "Moreover, the Dpy19l2 gene in KO mice also reproduced the infertile phenotype of globozoospermia with acrosomeless round-headed spermatozoa." (PMID 29065458, 2017). "Deletion of DPY19L2 gene accounted for 74% of individuals with globozoospermia." (PMID 27441053, 2016). "Partial or complete deletion of the DPY19L2 gene is pivotal factor in globozoospermia." (PMID 27441053, 2016). "We have previously reported that DPY19L2 genedeletion leads to globozoospermia." (PMID 27441053, 2016). "Finally, we also demonstrate the detection of a 160 Kb deletion containing the DPY19L2 gene in a patient who presented with suspected globozoospermia." (PMID 22912880, 2012). "In addition, the absence of DPY19L2, an inner nuclear membrane protein, causes globozoospermia in human and in mice by preventing the anchoring of the acrosome to the nucleus." (PMID 33198087, 2020). "Also genes in which mutations may lead to infertility, such as DPY19L2 or SPATA16, were proved to be associated with male infertility in human globozoospermia studies." (PMID 31671693, 2019). "Genetic defects in the DPY19L2 and SPATA16 genes have been identified in patients with partial globozoospermia, although the number of spherical spermatozoa is less than 50%." (PMID 39045326, 2024). "Genetic defects in the DPY19L2 and SPATA16 genes have been identified in our patients with partial globozoospermia, although the number of spherical spermatozoa is less than 50%." (PMID 39045326, 2024). "To date, several genes (most commonly DPY19L2, SPATA16) have been described in patients with isolated globozoospermia or globozoospermia combined with oligozoospermia." (PMID 39045326, 2024). "Globozoospermia is a rare male infertility disorder in which spermatozoa have round heads, abnormal or absent acrosomes, and are often defective in two genes, DPY19L2 and SPATA16." (PMID 38279344, 2024). "The genetic defects in the DPY19L2 and SPATA16 genes detected in patients from both globozoospermic groups suggest a generalized disruption of nuclear structure in globozoospermia, highlighting the genetic and phenotypic similarities between complete and partial globozoospermia." (PMID 39045326, 2024). "Although it is not clear whether DPY19L2 is a C-mannosyltransferase, impairment of the DPY19L2 gene was reported in patients with globozoospermia, in which sperm development is disturbed." (PMID 34500691, 2021). "Given the limited understanding of genetic mutations leading to globozoospermia in humans, we have also screened for exonic changes in KIAA0319L, in 16 patient samples already screened negative for deletions in the DPY19L2 gene, but have not found any pathogenic KIAA0319L mutation." (PMID 29991750, 2018). "We finally confirmed that the recurrent deletion observed in a majority of men with globozoospermia was caused by non-allelic homologous recombination (NAHR), between two highly homologous sequences, or low-copy repeats (LCR), located on each side of DPY19L2." (PMID 25780569, 2013).
Infertility (10 papers, 2016 to 2024). "Mutations in DPY19L2 are associated with an infertility disorder known as spermatogenic failure type 9 (SPGF9)." (PMID 32345215, 2020). "PI4KB (involved in actin formation), SOX2 (essential for early embryonic development) and DPY19L2 (causes infertility by impairing head elongation, PLCζ signalling, acrosome formation and by causing globospermia) were downregulated in crossbred males, in microarray." (PMID 32693775, 2020). "Recent genetic studies of infertility patients identified causative mutations in three genes: a protein interacting with C kinase 1 (PICK1), dpy 19-like 2 (DPY19L2), and spermatogenesis associated 16 (SPATA16)." (PMID 29065458, 2017). "First, all 16 patients were pre-screened for deletions and/or mutations in DPY19L2 and SPATA16, using a combination of targeted next-generation sequencing (NGS) and Sanger sequencing to detect point mutations and CNVs in these two genes and other known infertility genes." (PMID 31985809, 2020). "These genes play important roles in cell proliferation (RFX4, FOXM1, ASF1B), differentiation during spermatogenesis (CATSPERG, SPDYA, SPATA16, TSACC, TCP10L, DPY19L2) and motility of sperm cells during fertilization (DNAAF1); mutations in these genes may lead to infertility." (PMID 31671693, 2019).
male infertility (4 papers, 2019 to 2025). The inability of the male to effect fertilization of an ovum after a specified period of unprotected intercourse. "There are also male infertility cases caused by defects in single genes including CFTR, DDX3Y, SYCP3, TEX11, AURKC, and DPY19L2, but the number of genes confidently linked to male infertility remains very low." (PMID 34190021, 2022). "Several genetic mutations, including PRM1, AURKC, SPATA16, PICK1, DPY19L2, SEPT12, and SEPT14, result in male infertility and are caused by sperm DNA damage in a clinical context." (PMID 36295569, 2022).
Hearing impairment (1 paper, 2019). A decreased magnitude of the sensory perception of sound. "ATE1 (Unigene0043244), TPRN (Unigene0030527), TRIOBP (Unigene0033824), GREB1 (Unigene0021168), and DPY19L2 (Unigene0017291) are thought to be related to nonsyndromic hearing impairment by damaging structures in the inner ear." (PMID 31528181, 2019).
mental retardation (1 paper, 2013). "To this end we re-analysed the array CGH data produced for the diagnosis of syndromic mental retardation in Grenoble and Lyon hospitals, and searched for DPY19L2 deleted and duplicated alleles in this dataset." (PMID 23555282, 2013).
teratozoospermia (1 paper, 2021). "Our findings agree with those in previous literature, suggesting that DPY19L2 defects could contribute to this severe form of teratozoospermia." (PMID 34209343, 2021).
DPY19L2 also shares sentences with these, for which no sentence is quoted: macrozoospermia (2 papers); Bardet-Biedl syndrome (1); Obesity (1); retinopathy (1).